PTTG3P (pituitary tumor-transforming 3, pseudogene)
Diseases named in the same sentence as PTTG3P in open-access papers (continued):
Sharing a sentence is not in itself a finding about the gene and the disease.
cancer (14 papers, 2017 to 2025). A tumor composed of atypical neoplastic, often pleomorphic cells that invade other tissues. "While there is limited understanding of the biological roles of PTTG2, this protein, along with its associated counterpart, PTTG3P, has been implicated in the development of numerous human cancers." (PMID 40877987, 2025). "The upregulation of PTTG3P has been demonstrated to promote tumorigenesis by enhancing PTTG1 expression in cancer patients." (PMID 39139816, 2024). "PTTG3P, detected in various cancer types such as colorectal, tongue, and prostate cancer, shares high homology with the 3′ UTR of JAG1, an oncogenic protein that activates the NOTCH pathway." (PMID 37627052, 2023). "Pituitary tumor transforming genes (PTTG1, PTTG2, and PTTG3P) play key roles in the pathogenesis and development of human cancers." (PMID 33845847, 2021). "We revealed mRNA expressions of PTTG1, PTTG2, and PTTG3 which also named as PTTG3P in 20 types of cancers." (PMID 33173433, 2020). "In the group of other cancers, the highest fold change of PTTG3P was observed for UCEC (4.49) and the lowest for KIRP (0.09)." (PMID 32824814, 2020). "In the present study, we showed that PTTG3P was significantly overexpressed in GC tissues compared with ANTs, suggesting that this pseudogene has a cancer‐specific expression pattern in GC tissues." (PMID 28631396, 2017). "Our findings from the methylation analysis indicated that PTTG1, PTTG2, and PTTG3P exhibit hypomethylation in LUAD cells, which may underlie their increased expression, emphasizing the role of epigenetic modifications in cancer development." (PMID 40877987, 2025). "In addition, EDU proliferation assays showed that the cell proliferation capacity of cancer cells with silenced PTTG3P expression was significantly lower compared to the control group." (PMID 34660259, 2021). "Both PTTG1 and PTTG2 have been reported to serve oncogenic functions in human cancers 9, 10, 11, but the role of PTTG3P in GC remains unclear, and this pseudogene has previously been regarded as functionless." (PMID 28631396, 2017). "However, the exact mechanism by which lncRNA PTTG3P regulates cancer cell proliferation and migration in NSCLC is largely unknown." (PMID 37705754, 2023). "Besides, high PTTG3P expression was observed in other malignant tumors." (PMID 34132347, 2021). "In addition, high PTTG3P expression was observed in several types of malignant tumors." (PMID 34660259, 2021). "Thus, the oncogenic role of PTTG3P in malignant tumors is strongly suggested." (PMID 34132347, 2021). "However, there are only a few reports regarding the expression and roles of PTTG3P in cancer." (PMID 31011629, 2019). "Therefore, we supposed that PTTG3P exerted its roles in cancer by these biological processes." (PMID 31011629, 2019). "The results of PCR showed that the mRNA expression levels of PIP5K1P1, PTTG3P, and SNORD15B in the cancer cells were significantly higher than those in normal cells." (PMID 39170694, 2024). "In oral cancer, PTTG3P acts as a ceRNA for JAG1 by sponging miR-142-5p, leading to increased JAG1 translation and enhanced cancer cell proliferation." (PMID 37627052, 2023). "Previous studies have suggested that pituitary tumor-transforming 3, pseudogene (PTTG3P), serves as an oncogene in human cancers." (PMID 31011629, 2019). "PTTG2 and PTTG3P, being homologous to PTTG1, have roles not fully elucidated, but their confirmed association with human cancer development is acknowledged." (PMID 40877987, 2025). "However, for PTTG2 and PTTG3P, there are no significant changes observed across the stages (F values = 0.611 and 0.773, respectively; p = 0.608 and 0.51), indicating that these genes might not have a strong association with cancer stage progression in LUAD." (PMID 40877987, 2025). "We need to remember that patients with low expressions of PTTG3P, PTTG1 and PTTG2 have cancer." (PMID 32824814, 2020).
cancer (continued). "It proves that PTTG3P, PTTG1 and PTTG2 may function as oncogenes in HNSCC, similarly as was indicated in other cancers." (PMID 32824814, 2020). "The SAGE Digital Gene Expression Display showed no macroscopic differences in the expression of PTTG3P in the cancer and normal groups, partially because of the gene’s extremely low overall expression." (PMID 31011629, 2019). "It seems that the relationship between PTTG3P and PTTG1 varies in different cancers." (PMID 29803224, 2018). "Hence, PTTG3P might be a useful target for CRC prevention and therapy and may shed some light on the role of the poorly understood m6A and pseudogene in cancer biology." (PMID 34660259, 2021).
adenocarcinoma (1 paper, 2020). A common cancer characterized by the presence of malignant glandular cells. "In the group of adenocarcinomas, the highest fold change of PTTG3P was indicated for LUAD (3.09) and the lowest for STAD (0.15)." (PMID 32824814, 2020).
PTTG3P also shares sentences with these, for which no sentence is quoted: ovarian tumors (2 papers); pituitary tumor (2); stomach adenocarcinoma (2); colon adenocarcinoma (1); ductal breast carcinoma (1); ductal breast carcinoma in situ (1); head and neck squamous cell carcinoma (1); intraductal cribriform breast adenocarcinoma (1); invasive breast carcinoma (1); invasive ductal breast carcinoma (1); invasive lobular breast carcinoma (1); male breast carcinoma (1); medullary breast carcinoma (1); osteosarcoma (1); ovarian carcinoma (1); ovarian serous adenocarcinoma (1); prion disease (1); rectal adenocarcinoma (1); viral infection (1).